PPARG (peroxisome proliferator activated receptor gamma)
Diseases named in the same sentence as PPARG in open-access papers (continued):
Sharing a sentence is not in itself a finding about the gene and the disease.
liver fibrosis (continued). "A previous study showed that intrahepatic expression of PPARγ was significantly reduced in patients with liver fibrosis and cirrhosis." (PMID 38178856, 2023). "JMJD1A (Jumonji domain containing 1A) is a histone demethylase that has been shown in vitro and in vivo to modulate the activation of HSCs and liver fibrosis by affecting peroxisome proliferator-activated receptor gamma (PPARγ) gene expression." (PMID 37511164, 2023). "An antifibrotic effect of an ARB (Telmisartan), which is an angiotensin 1 (AT) receptor blocker and a PPARγ partial agonist, was demonstrated in both acute and chronic stages of a Schistosoma-mansoni-induced liver fibrosis mouse model." (PMID 37509613, 2023). "RA against liver fibrosis via inhibiting the expression and signaling of canonical Wnts/PPARγ in hepatic stellate cells." (PMID 35528835, 2022). "PPARγ is also a crucial transcriptional regulator of genes involved in lipid metabolism, liver fibrosis, fat metabolism and adipocyte differentiation for adipose tissue development and functional maintenance." (PMID 35308208, 2022). "PPARγ is encoded by the gene PPARG, and agonists of PPARG (e.g., IFC305 and pioglitazone) obstruct liver fibrosis by inhibiting HSC activation and regulating the expression of adipogenic- and fibrogenic-related genes." (PMID 35308208, 2022). "PPARγ also regulates inflammatory factors in the liver, but the promoter of PPARγ is hypermethylated both in liver inflammation and liver fibrosis, and thus its expression is reduced —although the oleuropein content of EVOO can counteract it." (PMID 35215560, 2022). "The formation of H3K27me3 in the 3’ exon of PPARG represses the anti-fibrotic effect of this gene and promotes hepatic fibrosis." (PMID 35844554, 2022). "A previous report has indicated that PPARγ plays a crucial role in protecting liver from diverse diseases such as hepatitis, liver fibrosis, liver cancer and NAFLD." (PMID 35565726, 2022). "Currently, Li and colleagues found that the miR-34 family participates in the process of hepatic fibrosis by regulating the Peroxisome proliferator-activated receptor γ (PPARγ) pathway." (PMID 33437196, 2021). "Collectively, these findings suggest that KLF14 suppression due to EZH2 elevation in fibrotic liver contributes to liver fibrosis progression by downregulating PPARγ." (PMID 34031939, 2021). "In this sense, the detection in ctDNA of two CpG sites differentially methylated at the promoter of the peroxisome proliferator-activated receptor γ gene (PPARγ) has been proposed to stratify liver fibrosis in patients with NAFLD." (PMID 33809263, 2021). "Collectively, our study suggests that KLF14 overexpression mitigates TAA‐induced rat liver fibrosis through PPARγ signalling." (PMID 34031939, 2021). "Adenovirus‐mediated KLF14 overexpression ameliorated TAA‐induced rat liver fibrosis in PPARγ‐dependent manner." (PMID 34031939, 2021). "Most PPARγ agonists can reduce hepatic fibrosis by restraining HSC proliferation and driving activated HSC to apoptosis." (PMID 34361064, 2021). "PPARγ agonists have been investigated as a treatment for liver fibrosis by inhibiting collagen production by activated HSCs, but enthusiasm has been limited by concern about weight gain induced by these agents." (PMID 34151243, 2021). "By mapping the candidate targets to the 66 known genes associated with hepatic fibrosis obtained from OMIM and DrugBank, 10 co-targets were found, including HSP90AA1, PPARG, MAPT, HSP90AB1, STAT1, and PPARA." (PMID 33510287, 2021).
liver fibrosis (continued). "Antihyperglycemic drugs, such as pioglitazone, a potent ligand of PPARγ, delay liver fibrosis and hepatocarcinogenesis in dietary NASH models and DEN-treated mice by enhancing AMPK pathways and mitobiogenesis." (PMID 33920670, 2021). "HSC activation is associated with decreased peroxisome proliferator-activated receptor γ (PPARγ) expression, while PPARγ agonists can reduce liver fibrosis in NASH patients." (PMID 33477873, 2021). "KLF14 reversed the activated HSCs to the quiescent phenotype and inhibited TAA‐induced liver fibrosis by transactivating PPARγ expression." (PMID 34031939, 2021). "The EZH2 inhibitor EPZ‐6438 rescues EZH2‐mediated KLF14 downregulation, which transactivates PPARγ expression, converts the activated HSCs to the quiescent phenotype and induces apoptosis, and therefore alleviating liver fibrosis." (PMID 34031939, 2021). "FXR agonists have been found to upregulate PPARγ expression and to decrease activation markers in HSCs in vitro, as well as to reduce hepatic fibrosis in vivo." (PMID 33807461, 2021). "More importantly, there existed a strongly positive correlation between KLF14 expression and PPARγ expression in patients with liver fibrosis." (PMID 34031939, 2021). "Taken together, KLF14 overexpression transactivated PPARγ, and therefore converting the activated HSCs to the quiescent phenotype, thus alleviating liver fibrosis." (PMID 34031939, 2021). "PPARγ ameliorate liver fibrosis and inhibit HSC proliferation regulating many transcription factors, such as CCAAT/enhancer binding protein (C/EBP), LXRα and SREBP-1c, which are depleted when HSCs are activated." (PMID 34361064, 2021). "Activation of HSCs drives hepatic fibrosis, and is inhibited by peroxisome proliferator-activated receptor gamma (PPARγ) signalling, in part through antagonism of Wnt activity." (PMID 34151243, 2021). "HSC-specific PPARγ deletion was shown to aggravate hepatic fibrosis, while PPARγ overexpression decreased HSC activation and fibrosis in vivo." (PMID 33807461, 2021). "Research-based evidence suggests that PPARγ mediates the effect of liver-protective docosahexaenoic acid in ameliorating liver fibrosis by inducing cell cycle arrest and apoptosis in HSCs." (PMID 34746195, 2021). "In animal studies, adenovirus‐mediated KLF14 overexpression ameliorated thioacetamide (TAA)‐established rat liver fibrosis through activating PPARγ signalling." (PMID 34031939, 2021). "Cross-regulation by PPARγ of key fibrogenic factor TGF-β1 signaling have been identified as a main mechanisms by which PPARγ inhibits liver fibrosis." (PMID 34660662, 2021). "We previously reported that the jumonji domain containing protein 1A (JMJD1A), also known as lysine demethylase 3A (KDM3A), modulates HSCs activation and liver fibrosis through demethylating H3K9me2 at PPARγ promoter and positively regulating its expression." (PMID 33391480, 2021). "Upon HSCs activation, the elevated EZH2 mediates suppression of KLF14 expression, which promotes HSCs activation and liver fibrosis by downregulating PPARγ." (PMID 34031939, 2021). "PPARγ activation inhibits hepatic fibrosis by inhibiting the TGF-β1/Smad pathway and significantly attenuates unilateral ureteral obstruction-induced renal interstitial fibrosis by reducing the expression of fibronectin, collagen IV, and TGF-β1." (PMID 34938805, 2021). "In summary, we have shown that a selective modulator of PPARγ was effective in reducing established hepatic fibrosis in a mouse model." (PMID 32630819, 2020). "By contrast, the HSC-specific ablation of PPARγ aggravates CCl4-induced liver fibrosis and increases αSMA expression." (PMID 32660130, 2020). "Because PPARγ is widely expressed in many cell types, it is possible that the reduction in hepatic fibrosis was the result of both direct and indirect actions." (PMID 32630819, 2020).
liver fibrosis (continued). "Transdifferentiation of HSCs into myofibroblasts is a key event in liver fibrosis, and this event is suppressed by peroxisome proliferator-activated receptor-gamma (PPARγ)." (PMID 33207561, 2020). "KDM3A can be able to regulate the activation of hepatic stellate cells and liver fibrosis via epigenetic regulation of PPARγ." (PMID 32092824, 2020). "In summary, a selective PPARγ modulator was effective in the reduction of established hepatic fibrosis and the activated phenotype of hepatic stellate cells." (PMID 32630819, 2020). "Puerarin effectively attenuated liver damage by up‐regulating PPARγ expression in CCl4‐induced hepatic fibrosis." (PMID 32031298, 2020). "The treatment of rats with NASH with the PPARγ agonist pioglitazone prevents hepatic fibrosis and reduces the expression of TIMPs." (PMID 32660130, 2020). "Telmisartan is a potential treatment for NAFLD due to its ability to improve insulin sensitivity and decrease hepatic fat accumulation via modulation of PPARγ, and to suppress hepatic fibrosis by blocking angiotensin II receptors." (PMID 30850637, 2019). "Other studies have documented the cross-talk between FXR and PPARγ in alleviating liver fibrosis and other metabolic diseases like nonalcoholic fatty liver disease." (PMID 31137621, 2019). "Meanwhile, the PPARγ agonist rosiglitazone (RSG) significantly antagonized hypoxia-induced development of hepatic fibrosis." (PMID 29686697, 2018). "One recent study has demonstrated that histone H3K9 demethylase JMJD1A (also called KDM3A) can act as a novel epigenetic regulator in modulating HSC activation and liver fibrosis by targeting PPARγ gene expression." (PMID 29954104, 2018). "Reduced expression of PPARG and concomitant decrease in PPAR-γ protein levels and signaling in HSCs associates with progression of liver fibrosis and increases collagen production." (PMID 29522534, 2018). "Several studies have demonstrated that inhibition of PPARγ can alleviate schistosomiasis hepatic fibrosis." (PMID 29094025, 2017). "Hepatic stellate cell (HSC) activation is a key step in liver fibrosis and peroxisome‐proliferator activated receptor γ (PPARγ) exerts a crucial role in inhibition of HSC activation." (PMID 27709831, 2017). "For example, the dopaminergic activities of haloperidol and chlorpromazine hydrochloride (both antipsychotic medications) and the PPARγ activity of farglitazar (a PPARγ agonist developed for treatment of hepatic fibrosis) were detected." (PMID 26978842, 2016). "In order to investigate the effect of overexpression of PPARγ on liver fibrosis in mice, one research group employed an adenovirus expressing PPARγ for transduction." (PMID 26941644, 2016). "The 34-mer PEDF can be injected directly into the peritoneal cavity to efficiently ameliorate CCl4-induced liver fibrosis in mice and induces PPARγ expression in activated HSCs." (PMID 24763086, 2014). "The present study has aimed at testing the efficacy of TELM, an AT1 receptor blocker and a PPARγ activator, in both acute and chronic stages of liver fibrosis induced in mice by S. mansoni infection." (PMID 23829789, 2013). "In hepatic fibrosis curcumin activated PPARγ which contributed to apoptosis and a reduction in extracellular matrix expression in hepatic stellate cells through the interruption of TGFß signaling and suppression of CTGF." (PMID 23437361, 2013). "Nine muscle pathways were identified, including inflammatory (hepatic fibrosis and IL-6), lipid metabolic (PPARα, PPARγ and sphingolipids) and carbohydrate metabolic (pyruvate and propanoate) pathways." (PMID 23251491, 2012). "This may reflect a direct involvement of PPARγ in mediating the beneficial effects of adiponectin on liver fibrosis, as overexpression of PPARγ2 alone at least partially recapitulated the phenotype of adiponectin overexpression in HSCs." (PMID 39792554, 2025).
liver fibrosis (continued). "Note, under hypoxic conditions and through upregulation of the transcription factor PPARγ, miRNA-27b plays an essential role in lipid metabolism while silencing of miRNA-125b-5p promotes liver fibrosis in MASLD via integrin α8-mediated activation of the RhoA signaling pathway." (PMID 39424772, 2025). "These experimental findings have recently been confirmed in vivo: HSC-specific PPARγ knockout mice are more sensitive to CCl4-induced hepatic fibrosis, and when the fibrogenic CCl4 agent is ceased, liver fibrosis in mice with specific PPARγ knockout resolves more slowly than in wild-type mice." (PMID 39063116, 2024). "Additionally, another anti-fibrotic gene repressed by EZH2 is peroxisome proliferator-activated receptor gamma (PPAR-γ), a ligand-activated transcription factor that promotes protective effects against including liver fibrosis." (PMID 39408226, 2024). "Because PPARγ is significantly decreased in HSC activation, upon HSC activation, PPARγ maintenance may be a strategy to treat liver fibrosis." (PMID 39200340, 2024). "We speculated whether the selective activation of PPARγ in hepatic macrophages could favor hepatic regeneration in the context of liver fibrosis." (PMID 37242695, 2023). "Overall, our results indicate that macrophage-selective PPARγ activation with DGNS-GW may polarize liver macrophages towards a pro-resolutive phenotype to stimulate extracellular matrix remodeling in liver fibrosis." (PMID 37242695, 2023). "In the current study, we provided evidence that treatment with SA ameliorates CCl4-induced liver fibrosis, at least in part by modulating M1/M2 macrophage polarization via activating PPARγ and by inhibiting oxidative stress-induced hepatocyte cell death in mice." (PMID 37760020, 2023). "Similarly, in the CCl4-induced liver fibrosis model, PPARγ deletion in KC reveals pro-inflammatory and pro-fibrotic responses, while such impacts are not found in hepatocyte-specific PPARγ knock-out mice." (PMID 37760020, 2023). "Upregulation of adrenic acid and arachidonic acid in serum and re-expression of PPARγ in HSCs may play a crucial role in liver fibrosis improvement." (PMID 38178856, 2023). "Additionally, activated PPARγ inhibits liver fibrosis-related inflammatory responses by increasing M2 macrophage polarization." (PMID 37760020, 2023). "Since macrophages play essential roles in the balance between fibrogenesis and regression and PPARγ agonists have been proven to reduce experimental liver fibrosis, we then evaluated the potential therapeutic utility of macrophage-targeted DGNS-GW in ECM remodeling in liver fibrosis." (PMID 37242695, 2023). "Moreover, both in rat models and in NAFLD patients, it was found that Pparγ methylation levels significantly correlated with the severity of liver fibrosis." (PMID 37190114, 2023). "Moreover, PPARγ viral overexpression has been reported to reduce CCl4-induced liver fibrosis in rats." (PMID 36339540, 2022). "It is well accepted that PPARγ is a key molecule involved in the pathogenesis of liver fibrosis." (PMID 35308208, 2022). "Activation of PPARγ by rosiglitazone also ameliorated bile duct ligation-induced liver fibrosis." (PMID 36339540, 2022). "We found that the PPARG signalling pathway could be regulated by SCST for liver fibrosis through enrichment analysis." (PMID 33510287, 2021). "Furthermore, in mice subjected to bile duct ligation rosiglitazone inhibited NF-kB activation and hepatic fibrosis, but these changes disappeared in Pparγ-DHEP mice." (PMID 34361064, 2021). "Antifibrotic miRNAs regulated by PPARγ during HCC-related liver fibrosis." (PMID 34638914, 2021). "Importantly, PPARγ can be activated by various ligands, such as fatty acids and thiazolidinedione, to inhibit HSCs proliferation and improve liver fibrosis." (PMID 34746195, 2021). "Moreover, the methylation level of Pparγ was found to be positively correlated with liver fibrosis levels in rat models as well as in NAFLD patients." (PMID 34572442, 2021).
liver fibrosis (continued). "The expression of the characteristic qHSC marker PPARγ is abolished during HSC activation, but the stimulation of PPARγ can halt aHSC proliferation, induce apoptosis, or reverse aHSCs to quiescent-like iHSCs, and it has been shown to ameliorate liver fibrosis in vivo." (PMID 33807461, 2021). "Collectively, EPZ‐6438 could alleviate TAA‐induced liver fibrosis by directly regulated PPARγ expression and indirectly regulated PPARγ expression via KLF14." (PMID 34031939, 2021). "Rosiglitazone could inhibit NF-κB activation and hepatic fibrosis after bile duct ligation in wild-type mice, but these changes disappeared in PpargΔHEP mice, suggesting a key role for PPARγ in the context of biliary fibrosis." (PMID 32192216, 2020). "The thiazolidinedione class of antidiabetic drugs, through their target peroxisome proliferator-activated receptor γ (PPARγ), have protective effects against liver fibrosis, and can inhibit the profibrotic activity of hepatic stellate cells, the major collagen-producing liver cells." (PMID 32630819, 2020). "Collectively, these findings clearly link decreased PPARγ activity in HSC to hepatic fibrosis." (PMID 32660130, 2020). "Therefore, while drugs targeting PPARγ showed promise in the prevention of hepatic fibrosis, they appear to be ineffective at treating established fibrosis." (PMID 32630819, 2020). "PPARγ agonists could reduce hepatic fibrosis by restraining HSC proliferation and driving activated HSC to apoptosis." (PMID 32192216, 2020). "Ligustrazine, which is an active component from Rhizoma Chuanxiong, could directly stimulate PPARγ by ligand activation to suppress the function of hepatic stellate cells in liver fibrosis." (PMID 33178326, 2020). "Plerixafor treatment blocks the SDF-1/CXCR4 axis, decreasing bone marrow cell migration to the liver and ameliorating liver fibrosis mainly through peroxisome proliferator-activated receptor gamma (PPARγ) and vascular endothelial growth factor (VEGF) expression increase." (PMID 31671842, 2019). "Therefore, PPARγ plays an important role in reducing and preventing liver fibrosis via inhibition of HSCs activation." (PMID 31795488, 2019). "EVs from HepG2 cells or primary mouse hepatocytes treated with palmitic acid contain enriched miRNAs including miR-128-3p which can activate HSCs through the attenuated expression of peroxisome proliferator-activated receptor gamma (PPARγ) leading to liver fibrosis." (PMID 31052525, 2019). "Furthermore, an increasing amount of evidence has established that PPARγ is a pivotal negative regulator of HSC activation in the pathogenesis of liver fibrosis." (PMID 29954104, 2018). "With further validation, plasma DNA methylation of PPARγ could potentially be used to non-invasively stratify liver fibrosis severity in patients with NAFLD." (PMID 27002005, 2017). "PPARγ agonists may directly inhibit proliferation of hepatic stellate cells and consecutive hepatic fibrosis." (PMID 29098441, 2017). "However, targeting PPARγ in preclinical animal models of liver fibrosis by treatment with TZDs has met with mixed results." (PMID 28620300, 2017). "With respect to hepatic fibrosis, PPARγ plays a central role in the activation of HSCs, as PPARγ expression alone is enough to restore the quiescent phenotype in activated HSCs and both activation and proliferation of HSCs correspond to exhausted PPARγ expression." (PMID 26941644, 2016). "In conclusion, our results suggest that 15d-PGJ2 plays a crucial role in homing of BMSCs to the injured liver dependent on ROS production, independently of PPARγ, which may represent a new strategy in the treatment of liver fibrosis." (PMID 26457076, 2015).